BHLHA9 (basic helix-loop-helix family member a9)
Description:
Transcription factor, which play a role in limb development. Is an essential player in the regulatory network governing transcription of genes implicated in limb morphogenesis.
Synonyms: bHLHf42; CCSPD
Tractability: No criterion of Open Targets' tractability assessment is met for any kind of drug.
Gene: Protein-coding gene on chromosome 17 (1,270,444 to 1,271,815, forward strand). Ensembl gene ENSG00000205899.
Subcellular location: Nucleus; Cytoplasm
Gene Ontology:
Molecular function: protein binding; protein heterodimerization activity; DNA-binding transcription factor activity, RNA polymerase II-specific; RNA polymerase II transcription regulatory region sequence-specific DNA binding; protein dimerization activity
Biological process: developmental process; regulation of transcription by RNA polymerase II
Cellular component: cytoplasm; chromatin; nucleus
Genetic constraint (gnomAD): Loss-of-function variants: 1 observed, 0.44 expected, observed/expected ratio (o/e) 2.25. That is too few expected variants to judge how well the gene tolerates losing a copy. Missense variants: 341 observed, 225.42 expected, observed/expected ratio (o/e) 1.51, 90% interval 1.38 to 1.65. Synonymous variants: 176 observed, 103.66 expected, observed/expected ratio (o/e) 1.7, 90% interval 1.5 to 1.91.
Homologues: Orthologues: chimpanzee BHLHA9 (99% identical), rabbit BHLHA9 (74% identical), pig BHLHA9 (72% identical), rat Bhlha9 (69% identical), mouse Bhlha9 (66% identical), guinea pig BHLHA9 (63% identical), zebrafish bhlha9 (37% identical), Drosophila melanogaster CG33557 (15% identical), Caenorhabditis elegans hlh-8 (13% identical), Drosophila melanogaster HLH54F (12% identical), Drosophila melanogaster twi (11% identical), Drosophila melanogaster Hand (10% identical). Paralogues in human: SCX (20% identical), TCF15 (19% identical), PTF1A (18% identical), TWIST1 (16% identical), TCF21 (15% identical), TWIST2 (15% identical), TCF23 (15% identical), TCF24 (15% identical), FIGLA (14% identical), HAND1 (14% identical), MSC (14% identical), FERD3L (14% identical), and 1 more.
Diseases named in the same sentence as BHLHA9 in open-access papers:
BHLHA9 is named in the same sentence as 11 diseases in open-access papers, as found by Europe PMC text mining. Sharing a sentence is not in itself a finding about the gene and the disease. The quoted sentences say what the papers report.
complex camptosynpolydactyly (1 paper, 2025). "In contrast, homozygous loss-of-function mutations in BHLHA9, including missense and frameshift variants, have been linked to MSSD and complex camptosynpolydactyly." (PMID 40822683, 2025). "To date, BHLHA9 has been implicated in three distinct limb phenotypes: split-hand/foot malformation with long bone deficiency (SHFLD3, OMIM#612576), complex camptosynpolydactyly (OMIM#607539), and MSSD." (PMID 40822683, 2025).
mesoaxial synostotic syndactyly with phalangeal reduction (1 paper, 2019). "In contrast, loss-of-function mutations of BHLHA9 lead to mesoaxial synostotic syndactyly with phalangeal reduction (MSSD, Type 9 human syndactyly, OMIM 609432)." (PMID 31637260, 2019).
SHFLD syndrome (1 paper, 2012). "In another study, seventeen patients with 17p13.3 duplication, among 56 families with SHFLD syndrome, showed a minimal critical region encompassing the BHLHA9 gene." (PMID 23035971, 2012).
syndactyly (1 paper, 2022). A disease characterized by the presence of syndactyly, including syndromic and non-syndromic forms. "Candidate gene studies on HOXD13, LMBR1, FGF16, BHLHA9, to understand their contribution to both cutaneous and synostosis syndactyly phenotypes, could enhance screening." (PMID 35549993, 2022).
BHLHA9 also shares sentences with these, for which no sentence is quoted: Gollop-Wolfgang complex (2 papers); autism (1); developmental delay (1); frontonasal dysplasia (1); neurological disorders (1); Poland syndrome (1); sirenomelia (1).